MEG8 (maternally expressed 8, small nucleolar RNA host gene)
Synonyms: NCRNA00024; Irm; Rian; Bsr; LINC00024; AL132709.8; lnc-MGC; formerly SNHG23; SNHG24
Gene: Long non-coding RNA gene on chromosome 14 (100,883,057 to 101,038,859, forward strand). Ensembl gene ENSG00000225746.
Gene Ontology:
Biological process: cellular response to leukemia inhibitory factor; miRNA-mediated post-transcriptional gene silencing; negative regulation of gene expression; RNA processing
Cellular component: nucleolus; nucleus; RISC complex
Diseases named in the same sentence as MEG8 in open-access papers:
MEG8 is named in the same sentence as 50 diseases in open-access papers, as found by Europe PMC text mining. Sharing a sentence is not in itself a finding about the gene and the disease. The quoted sentences say what the papers report.
lung carcinoma (6 papers, 2021 to 2022). "The nine downregulated C/D snoRNAs represented 3.6% of the expressed C/D snoRNAs and were all part of the highly duplicated SNORD113-SNORD114 families embedded within the introns of lncRNA MEG8, which was previously linked to pancreatic and lung cancer epithelial to mesenchymal transition (EMT)." (PMID 35047824, 2022). "Another study in lung cancer has shown up-regulation of MEG8, parallel with down-regulation of miR-15a-5p and miR-15b-5p in cancer cell lines." (PMID 36114498, 2022). "MEG8 silencing has suppressed proliferation, migration, and invasion of lung cancer cells through targeting miR-15a-5p/miR-15b-5p." (PMID 36114498, 2022). "For example, overexpression of MEG8 has been shown to induce transcriptional repression of miRNA-34a and miRNA-203 in human lung cancer cells." (PMID 35611612, 2022). "On the other hand, MEG8 knockdown or miR-107 up-regulation has blocked cell progression of lung cancer cells." (PMID 36114498, 2022). "Studies in xenograft models of lung cancer have confirmed that MEG8 enhances tumor growth through modulation of miR-15a/b-5p/PSAT1." (PMID 36114498, 2022). "Expression of MEG8 has been found to be increased in tissue samples obtained from lung cancer patients compared to corresponding normal tissues." (PMID 36114498, 2022). "It has been reported that lncRNA MEG8 contributes to the epigenetic progression of epithelial-mesenchymal in both pancreatic and lung cancer cells, and suppresses the growth and migration of trophoblast cells and vascular smooth muscle cells." (PMID 34477472, 2021). "It has been reported that lncRNA MEG8 enhances the epithelial-mesenchymal transition by modulating epigenetic progression in pancreatic and lung cancer cells." (PMID 33526036, 2021). "MEG8 silencing has considerably decreased tumor growth and burden in animal models of lung cancer." (PMID 36114498, 2022). "Moreover, they have transfected lung cancer A549 and H1299 cells with MEG8 or miR-107 overexpressing vectors as well as knockdown plasmids." (PMID 36114498, 2022). "Taken together, MEG8 could enhance progression of lung cancer through regulation of miR-107/CDK6 axis and activation of Rb/E2F3 pathway." (PMID 36114498, 2022). "For example, lncRNA MEG8, mainly induced by the TGF-β factor, is significantly upregulated in lung cancer and pancreatic cancer and can downregulate miR-34a to repress E-cadherin expression." (PMID 35819532, 2022). "Their functional studies have confirmed competitive binding of MEG8 and CDK6 with miR-107 and their function in regulation of progression of lung cancer." (PMID 36114498, 2022). "MEG8 can also regulate EMT progression by activating TGF-β in pancreatic cancer and lung cancer." (PMID 35819532, 2022).
gestational diabetes (3 papers, 2021 to 2023). Carbohydrate intolerance first diagnosed during pregnancy. "The lncRNA MEG8 is dysregulated in several disorders, such as lung, ovarian and colorectal cancers, as well as gestational diabetes mellitus, diabetic nephropathy and ischemic heart disease." (PMID 38203310, 2023). "Some scholars have also found that MEG8 is up-regulated in the plasma of patients with gestational diabetes, which is helpful to predict the degree of kidney injury." (PMID 34790697, 2021). "Recent research has shown that MEG8 expression is upregulated in gestational diabetes mellitus (GDM) and predicts kidney injury." (PMID 34712322, 2021).
ischemic stroke (3 papers, 2020 to 2025). A stroke disorder caused by obstruction of blood flow to the brain, due to thrombotic (local blood clot formation) or embolic (due to a blood clot or other material traveling from another site) event. "MEG8 regulates angiogenesis and alleviates cerebral ischemia after ischemic stroke by targeting the miR-130a-5p/VEGFA pathway." (PMID 41219994, 2025). "MEG8 participates in the pathoetiology of different disorders ranging from neoplastic ones to diabetic nephropathy, atherosclerosis, ischemic stroke, trophoblast dysfunction and abortion, Henoch-Schonlein purpura and osteoarthritis." (PMID 36114498, 2022). "Recent studies have shown contribution of MEG8 in different disorders ranging from neoplastic ones to diabetic nephropathy, atherosclerosis, ischemic stroke, trophoblast dysfunction and abortion, Henoch-Schonlein purpura and osteoarthritis." (PMID 36114498, 2022). "In addition, MEG8 showed a trend towards upregulation in ischemic stroke and affected disease progression by regulating vascular endothelial cell viability, migration and angiogenesis." (PMID 41219994, 2025).
ovarian carcinoma (3 papers, 2021 to 2025). A malignant neoplasm originating from the surface ovarian epithelium. "On the other hand, an in silico approach in ovarian cancer has shown that the expression of MEG8 is associated with to better overall survival in Kaplan-Meier analysis." (PMID 36114498, 2022). "More importantly, it was found that elevated MEG8 levels predict venous thromboembolism in ovarian cancer patients." (PMID 41219994, 2025). "Bioinformatics analysis revealed that MEG8 is involved in ovarian cancer progression by regulating miR-378d." (PMID 41219994, 2025). "Similar to ovarian cancer, expression of MEG8 has been found to be down-regulated in colorectal cancer samples compared with controls." (PMID 36114498, 2022). "This approach has led to identification of the MEG8/miR-378d/SOBP axis as a functional axis in progression and prognosis of ovarian cancer." (PMID 36114498, 2022). "Our study establishes a novel MEG8/miR‐378d/SOBP axis in the development and prognosis of ovarian cancer, and the triple sub‐network probably affects the progression of ovarian tumor by regulating cytokines pathway." (PMID 33742531, 2021).
adenoma (2 papers, 2019 to 2021). A neoplasm arising from the epithelium. "In colorectal cancer, MEG8 may have a regulatory role in the adenoma-carcinoma transition." (PMID 34016788, 2021). "As in the case of certain presumably ‘driver’ lncRNAs (e.g. MEG8) in the present study, a distinct expression tendency could be detected in adenoma and carcinoma samples, so that their dysregulation may not be a gradual event during cancer formation." (PMID 31694571, 2019).
breast carcinoma (2 papers, 2021 to 2024). "Breast cancer cells that overexpress MEG8 also showed a lower proportion of CD44 + CD24- cells, which are considered tumor-initiating cells in breast tumors, except from MDA-MB-468." (PMID 39706842, 2024). "In this work, we described for the first time Rian/MEG8 as a possible biomarker connecting aging and breast cancer." (PMID 39706842, 2024). "In this work, we identified Rian/MEG8 as a potential biomarker connecting aging and breast cancer for the first time." (PMID 39706842, 2024). "Then, we found that the overexpression of MEG8 decreases the proliferative capacity of breast cancer cells both by activating a programmed cell death program such as apoptosis." (PMID 39706842, 2024). "We found that the overexpression of MEG8 decreases the number of CSCs and the stemness properties of breast cancer cell lines." (PMID 39706842, 2024). "Breast cancer cells that overexpress MEG8 grew slower, therefore, we wondered if they would have activated a programmed cell death." (PMID 39706842, 2024). "We found that MEG8 expression was higher in MCF10A in comparison with the three breast cancer cell lines and that this expression was lower in MDA-MB-468 and MDA-MB-231, two cell lines from basal/triple negative tumors, than in T47D, a luminal cell line." (PMID 39706842, 2024). "Next, we performed a growth curve assay, and we observed that cells that overexpress MEG8 grew slower than control cells in all breast cancer cell lines." (PMID 39706842, 2024). "For that purpose, we analysed the levels of MEG8 in patients with breast carcinoma from the database TCGA and we observed that breast tumor samples expressed lower levels of MEG8 than normal breast samples." (PMID 39706842, 2024). "Since the levels of MEG8 expression were low in the three breast cancer cell lines and they decrease with age and as the cell line was more tumorigenic, we overexpressed MEG8 and an empty vector (EV) as a control to study the role of MEG8 in breast tumors." (PMID 39706842, 2024). "Thus, the overexpression of MEG8 seems to decrease the proliferative capacity of the breast cancer cells in vitro." (PMID 39706842, 2024). "Therefore, it seems that breast cancer cells with increased MEG8 had activated a programmed cell death." (PMID 39706842, 2024). "Furthermore, MEG8 overexpression reduced the proliferative and stemness properties of breast cancer cells both in vitro and in vivo by activating apoptosis." (PMID 39706842, 2024). "Additionally, we found that breast cancer cells that overexpress MEG8 have decreased the expression levels of some stem cell markers such as BMI1, SOX9 and KLF4 and in some cases also NANOG or SOX2, but not OCT4." (PMID 39706842, 2024). "Therefore, MEG8 could be the link of senescence, aging and breast cancer, and this effect could be mediated by SOX9." (PMID 39706842, 2024). "Additionally, we analysed the levels of MEG8 and SNORD112 in patients from different breast cancer databases and we found that in most of the databases the mean of MEG8/SNORD112 expression of patients was lower than the mean of expression of the normal breast tissue database." (PMID 39706842, 2024). "Therefore, we focused on elucidating the role of MEG8 in the connection of aging and breast cancer." (PMID 39706842, 2024). "Next, we studied the expression levels of MEG8 and SNORD112 in a panel of three different breast cancer cell lines: T47D, MDA-MB-468 and MDA-MB-231; and we also include the non-tumorigenic cell line of epithelial breast tissue MCF10A." (PMID 39706842, 2024). "This correlated with a decreased expression of MEG8 observed in breast tumors in comparison with normal tissue from breast cancer patients of the TCGA database and the fact that the cluster DLK1-MEG8 has been found silence in several types of cancer." (PMID 39706842, 2024).
breast carcinoma (continued). "We found that the overexpression of MEG8 induced an increase in the percentage of apoptotic cells in the three breast cancer cell lines studied but we did not found differences in the percentage of necrotic cells." (PMID 39706842, 2024). "Cells that overexpress MEG8 formed lower number of holoclones (enriched in cancer stem cells, CSCs) and higher number of paraclones (colonies enriched in mature, non-stem cells) than control cells in all breast cancer cell lines, but we did not observe differences in MCF10A." (PMID 39706842, 2024).
diabetic nephropathy (2 papers, 2022 to 2023). "Taken together, MEG8 can increase miR-770-5p levels via epigenetic mechanism to induce diabetic nephropathy through enhancing cell apoptosis." (PMID 36114498, 2022).
Henoch-Schonlein purpura (2 papers, 2021 to 2022). "Herein, we aimed to explore whether maternally expressed gene 8 (MEG8) promotes M1 macrophage polarization among Henoch-Schonlein purpura (HSP) rats, and to investigate the underlying mechanism." (PMID 34477472, 2021). "MEG8 can also contribute in the pathogenesis of Henoch Schonlein purpura through sponging miR-181a-5p, influencing levels of SHP2 expression and increasing M1 macrophage polarization." (PMID 36114498, 2022).
hepatocellular carcinoma (2 papers, 2009 to 2022). A malignant tumor that arises from hepatocytes. "Expression of MEG8 has been found to be elevated in hepatocellular carcinoma (HCC) cells." (PMID 36114498, 2022).
ischemia (2 papers, 2022 to 2024). A hypoperfusion of the BLOOD through an organ or tissue caused by a PATHOLOGIC CONSTRICTION or obstruction of its BLOOD VESSELS, or an absence of BLOOD CIRCULATION. "We conclude that regulation of TFPI2 by MEG8 occurs both under basal conditions in the endothelium as well as during ischemia." (PMID 35039572, 2022). "Our study further highlights the MEG8/TFPI2 axis as potential therapeutic approach to improve angiogenesis in ischemia." (PMID 35039572, 2022). "Our study highlights the MEG8/TFPI2 axis as potential therapeutic approach to improve angiogenesis following ischemia." (PMID 35039572, 2022). "Taken together, these results point to a possible protective role for MEG8 in ischemia." (PMID 35039572, 2022).
Temple Syndrome (2 papers, 2022 to 2024). "Temple Syndrome (TS14) is a human imprinting disorder (ID) characterized by increased expression of the ncRNA polycistron, affecting MEG3, MEG8 (called Rian in the mouse) and MIRG RNA levels." (PMID 38613389, 2024). "A single study in patients with Temple syndrome has shown that DNA-methylation of the MEG3- and MEG8- differentially methylated region depends on the DNA-methylation pattern of the IG-differentially methylated region." (PMID 36114498, 2022).
abortion (1 paper, 2021). the ending of pregnancy by removing a fetus or embryo before it can survive outside the uterus. "In addition, MEG8 is highly expressed in human spontaneous abortion villi, and overexpressing MEG8 induces abortion and trophoblast cell dysfunction." (PMID 34790697, 2021).
acute leukemia (1 paper, 2023). A clonal (malignant) hematopoietic disorder with an acute onset, affecting the bone marrow and the peripheral blood. "SNORD113 and SNORD114 families are encoded within maternally-imprinted host gene MEG8 and are enriched in acute leukemia, suggesting a possible role in oncogenesis." (PMID 36806717, 2023).
breast tumors (1 paper, 2024). "Senescent cells accumulate with age, therefore MEG8 could be the result of the antagonistic pleiotropic theory, in which cellular senescence is beneficial early in life as a result of a tumor suppression mechanism because MEG8 is increased and causing few breast tumors with aging." (PMID 39706842, 2024). "We also observed decreased MEG8 expression in breast tumors compared to normal tissue." (PMID 39706842, 2024). "Indeed, we also observed that breast tumors presented a higher proportion of shallow or deep deletions in the gene MEG8 than the proportion of gains or amplifications." (PMID 39706842, 2024). "MEG8 could exemplify the antagonistic pleiotropic theory, where senescence is beneficial early in life as a tumor suppression mechanism due to increased MEG8, resulting in fewer breast tumors at an early age." (PMID 39706842, 2024).
Cerebral ischemia (1 paper, 2022). Restriction of arterial blood supply to the brain associated with insufficient oxygenation to support the metabolic requirements of the tissue. "Furthermore, loss of Meg8 was shown to impair angiogenesis in the mouse, while overexpression of Meg8 was shown to be protective in a rat cerebral ischemia model." (PMID 35039572, 2022).
chordoma (1 paper, 2017). Chordomas are rare malignant tumors arising from embryonic remnants of the notochord in axial skeleton. "Our lncRNA-coding genes profile data showed that the most differentially expressed protein coding gene in chordoma was DLK1, and Cis-regulation analysis revealed that this gene was targeted by a bunch of lncRNAs, most of which were identified to be different transcripts of MEG3 and MEG8." (PMID 29348851, 2017).
deep vein thrombosis (1 paper, 2025). "This study explored the diagnostic value and molecular mechanism of lncRNA MEG8 in deep vein thrombosis (DVT)." (PMID 41219994, 2025).
endothelial dysfunction (1 paper, 2022). In vascular diseases, endothelial dysfunction is a systemic pathological state of the endothelium (the inner lining of blood vessels) and can be broadly defined as an imbalance between vasodilating and vasoconstricting substances produced by (or acting on) the endothelium. "We hypothesize that MEG8 is a protective molecule in the endothelium that is induced upon aging to prevent further endothelial dysfunction." (PMID 35611612, 2022).
epilepsy (1 paper, 2025). A brain disorder characterized by episodes of abnormally increased neuronal discharge resulting in transient episodes of sensory or motor neurological dysfunction, or psychic dysfunction. "RNA-seq analysis of the iPSCs revealed that genes such as TTTY14, TBL1Y, MEG8, MEG9, BCORP1, and RPS4Y1 are not directly related to epilepsy." (PMID 40600194, 2025).
hemangioma (1 paper, 2023). A benign vascular lesion characterized by the formation of capillary-sized or cavernous vascular channels. "In addition, NOTCH2 is regulated by silencing long-chain noncoding RNA MEG8 to induce ferroptosis in hemangiomas." (PMID 37978473, 2023).
liver cancer (1 paper, 2026). An epithelial or non-epithelial malignant neoplasm that arises from the liver. "Analysis of clinical samples revealed that the expression levels of SNHG1, SNHG3‐7, SNHG16, SNHG20, and MEG8 (Maternally expressed 8, also known as SNHG23) are associated with clinical indicators of liver cancer patients." (PMID 41474641, 2026).
liver fibrosis (1 paper, 2022). "MEG8 was confirmed to suppress hepatic stellate cells activation and epithelial–mesenchymal transition (EMT) of hepatocytes in liver fibrosis via the Notch pathway." (PMID 34968168, 2022).
myocardial hypertrophy (1 paper, 2026). "Presumably, the downregulation of MEG8 in HCM may promote cardiac fibrosis and further aggravate myocardial hypertrophy." (PMID 41602333, 2026).
nasopharyngeal carcinoma (1 paper, 2025). A carcinoma arising from the nasopharyngeal epithelium. "Similar to AGS-EBV-Z cells, reactivation of HONE1-Akata-Z and NPC43-Z nasopharyngeal carcinoma cell lines led to greatly increased levels of MEG8, MEG9, and MIR381HG (respectively)." (PMID 40674434, 2025). "We showed that the lncRNAs MEG9, MIR381HG, and MEG8, from which miR-409-3p, miR-381-3p and miR-370-3p are derived, were also upregulated upon reactivation in AGS and nasopharyngeal carcinoma cells lines and occurred very early in the lytic cycle at the time of BZLF1 expression." (PMID 40674434, 2025).
osteosarcoma (1 paper, 2016). A usually aggressive malignant bone-forming mesenchymal neoplasm, predominantly affecting adolescents and young adults. "To evaluate the co-expression of imprinted genes and miRNAs at the 14q32 locus, we analyzed the expression of DLK1-DIO3 cluster genes (DIO3, DLK1, MEG3, and MEG8) and representative 14q32 miRNAs (miR-134, miR-154, and miR-382) in an independent set of 43 osteosarcoma tumor samples." (PMID 26802029, 2016).
pituitary adenomas (1 paper, 2021). "The current study aimed to investigate the role of MEG8/miR-454-3p/TNF-α in bone-invasive pituitary adenomas (BIPAs)." (PMID 34016788, 2021). "The correlation between MEG8 and miR-454-3p expression, miR-454-3p and TNF-α expression, MEG8 and TNF-α in pituitary adenomas were analyzed according to RT-qPCR results." (PMID 34016788, 2021).
renal fibrosis (1 paper, 2021). A final common manifestation of a wide variety of chronic kidney diseases characterized by glomerulosclerosis and tubulointerstitial fibrosis. "Moreover, lncRNA MEG8 downregulates the expression of Smad2, Smad3, Colla1 and α-SMA, and leads to the formation of myofibroblasts, which ultimately alleviates the progression of renal fibrosis." (PMID 34477472, 2021).
sarcoma (1 paper, 2023). A usually aggressive malignant neoplasm of the soft tissue or bone. "CASC9, LINC00922, LINC00511, MEG3, MEG8, and SNHG16 were significantly related to the poor prognosis of sarcoma patients." (PMID 36816047, 2023).